ENSG00000268107 (novel transcript)
Gene: Protein-coding gene on chromosome 19 (57,487,718 to 57,517,559, forward strand). Ensembl gene ENSG00000268107.
Genetic constraint (gnomAD): Missense variants: 70 observed, 68.91 expected, observed/expected ratio (o/e) 1.02, 90% interval 0.84 to 1.24. Synonymous variants: 29 observed, 29.25 expected, observed/expected ratio (o/e) 0.99, 90% interval 0.74 to 1.35.